DNMT3B (DNA methyltransferase 3 beta)
Diseases named in the same sentence as DNMT3B in open-access papers (continued):
Sharing a sentence is not in itself a finding about the gene and the disease.
ovarian carcinoma (continued). "In this study, we collected 142 cases of epithelial ovarian carcinoma samples and 44 cases of benign ovarian tumors for detection of DNMT1, DNMT3a, and DNMT3b protein expressions in order to determine the role of DNMT proteins in ovarian cancer and clinical significance." (PMID 22768205, 2012). "Targeting DNMT3B-mediated epigenetic reprogramming, either alone or in combination with piRNA-directed therapies, may therefore represent a potential avenue for future therapeutic development in ovarian cancer." (PMID 41596471, 2026). "Furthermore, HDAC1, HDAC2 and DNMT3b cooperated in controlling ovarian cancer progression and the HDACs may upregulate the expression of DNMTs." (PMID 23420051, 2013). "In addition, HDAC1, HDAC2 and DNMT3b cooperated in controlling ovarian cancer progression." (PMID 23420051, 2013). "Our integrated computational and clinical analyses indicate that the piR-823/PIWIL1/DNMT3B/CDH1 axis is a putative epigenetic regulator of EMT and cancer stemness in ovarian cancer." (PMID 41596471, 2026). "The heatmap revealed that PIWIL1, DNMT3B, OCT4, NANOG, and CDH2 were increased in most ovarian cancer samples, while CDH1 was downregulated, thus delineating clear expression differences between cancer and control samples." (PMID 41596471, 2026). "Surprisingly, higher expressions of DNMT3B and EZH2 are reported in ovarian cancer and, as per RNA-seq results, CHD4 expression is positively correlated with EZH2 in ovarian cancer patients." (PMID 40004553, 2025). "We next analysed the relationship between CHD4 and methylation enzymes (DNMT1, DNMT3B, EZH2, and G9a) in ovarian cancer." (PMID 36681835, 2023). "By regulating the DNMT3B-mediated DNA methylation of RBP1, miRNA-20a-5p can limit autophagy in ovarian cancer patients, decreasing their sensitivity to CDDP." (PMID 36766800, 2023). "A notable aspect of our results is that the level of DNMT3b was correlated with HDAC1 and HDAC2 in ovarian cancer, which demonstrated that the two epigenetic events cooperated in controlling ovarian cancer progression." (PMID 23420051, 2013). "The mRNA expression of DNMT1, DNMT3b, HDAC1 and HDAC2 were particularly prominent in high-grade tumors in ovarian cancers, which indicated that they may be the biomarkers of tumor aggressiveness and proliferation, as their high expression is closely associated with ovarian carcinoma progression." (PMID 23420051, 2013). "Top anti-correlated genes of miR-29 in ovarian cancer included DNMT3A and DNMT3B, suggesting a similar role for miR-29 in high-grade serous ovarian cancer." (PMID 22479643, 2012). "However, although several previous studies have shown that expression levels of DNMT3b mRNA and protein were increased in a variety of malignant tumors, our current data demonstrated a lower expression of DNMT3b in ovarian cancer tissues compared to that of benign tumor." (PMID 22768205, 2012). "In summary, we obtained novel evidence showing that low expression levels of ALDH1A2 are correlated with an early tumor stage and poor prognosis for ovarian cancer patients, and that its expression is negatively regulated by the methylation of ALDH1A2 via DNMT1 or DNMT3B." (PMID 31615043, 2019). "Furthermore, the expression of DNMT1, DNMT3b, HDAC1 and HDAC2 was significantly higher in stage III/IV compared with stage I/II ovarian carcinomas." (PMID 23420051, 2013). "Therefore, we evaluated the possible association of single nucleotide polymorphisms (SNPs) of DNA methyltransferases (DNMTs) genes, including DNMT1, DNMT3B, and DNMT3A, with ovarian cancer development in the Polish population." (PMID 23666104, 2013). "The results indicated that the mRNA expression of DNMT1, DNMT3b and class I HDACs was increased in ovarian cancers, while the expression of DNMT3a was not different between cancer tissues and normal ovaries." (PMID 23420051, 2013).
ovarian carcinoma (continued). "Haplotype analysis of DNMT1, DNMT3B, and DNMT3A polymorphisms did not reveal SNP combinations associated with the risk of ovarian cancer development." (PMID 23666104, 2013). "In ovarian cancer cell lines, knock-down of DNMT1 and DNMT3b, resulting in loss of CpG hypermethylation, has a negative effect on growth." (PMID 21943380, 2011). "However, none of the other nine studied DNMT1, DNMT3B and DNMT3A SNPs exhibited significant association either in dominant or recessive inheritance models with ovarian cancer development." (PMID 23666104, 2013). "Furthermore, haplotype and multifactor dimensionality reduction analysis of the studied DNMT1, DNMT3B, and DNMT3A polymorphisms did not reveal either SNP combinations or gene interactions to be associated with the risk of ovarian cancer development." (PMID 23666104, 2013). "One of the first studies of DNMT expression in ovarian tumors used cancer cell lines and showed an increased expression of DNMT1 and DNMT3B, but not DNMT3A mRNA levels, in ovarian cancer cell lines compared to normal ovarian surface epithelial cells." (PMID 37894317, 2023). "siRNA silencing of DNMT1 or DNMT3B restored the expression of ALDH1A2 and reduced methylation in ovarian cancer cells, whereas no significant changes in ALDH1A2 expression were observed upon knockdown of DNMT3A." (PMID 31615043, 2019).
glioma (23 papers, 2011 to 2024). A benign or malignant brain and spinal cord tumor that arises from glial cells (astrocytes, oligodendrocytes, ependymal cells). "To study the role of DNMTs in gliomas, we used q-RT PCR to analyze the expression of the three DNA methyltransferase enzymes (DNMT1, DNMT3A and DNMT3B) in a panel of low and high-grade gliomas (n=32) collected at the University Medical Center Freiburg." (PMID 28036297, 2017). "In glioma cells, corecruitment of Dnmt1, Dnmt3b and HDAC1 on the TMS1 promoter suggest a silencing complex requiring a cooperation between DNA methylation and hypoacetylation." (PMID 24709797, 2013). "Data describing DNMT mRNA expression inmalignant glioma are extremely scarce, indicating an up-regulation of at least DNMT1and DNMT3b in GBM tissue samples as compared to normal brain." (PMID 21365007, 2011). "Their discoveries uncovered the significant contributions of circRNA_104948 in the progression of glioma, highlighting that the circRNA_104948/miR-29b-3p/MTSS1/DNMT3B pathway holds promise as a potential therapeutic target for individuals diagnosed with glioma." (PMID 37705098, 2023). "At the same time, it is found that circRNA_104948/miR-29b-3p/MTSS1/DNMT3B pathway may be a potential candidate for targeted therapy in patients with glioma." (PMID 37934565, 2023). "Moreover, it has been reported that DNMT1 and DNMT3B are overexpressed in gliomas and inhibiting DNMTs by 5-azacytidine (azacytidine, DNMT inhibitor) enhances expression of tumor suppressor genes such as p21." (PMID 31500384, 2019). "Furthermore, DNA methyltransferase DNMT1, involved in the maintenance and self-renewal of progenitor cells in somatic tissues, and DNMT3B are up-regulated in gliomas." (PMID 23888189, 2012). "Applying univariant and multivariant CoxPH analysis, we proved that ALYREF, DNMT3B, NSUN4 and NSUN6 were independent prognostic factors for glioma." (PMID 37934565, 2023). "The results showed that NSUN4, NSUN7, DNMT1, DNMT3B, DNMT3A, NOP2 and NSUN5 were negatively correlated with the overall survival of low‐grade glioma, while NSUN6 was positively correlated with the overall survival." (PMID 33400376, 2021). "OCT4 expression was shown to correlate with DNMT1 and DNMT3b expression in primary glioblastoma neurosphere, and the transgenic OCT4/SOX2 co-expression is able to increase the expressions of DNMTs in gliomas." (PMID 31771617, 2019). "CD133 knockdown increased the nuclear translocation of DNMT1 in CD133+ glioma cells without obviously changing the nuclear translocation of DNMT3a or DNMT3b." (PMID 35798319, 2022). "Our data indicated that the use of an unspecific DNMT inhibitor (5aza-2deoxycytidine), a DNMT1 inhibitor (procainamide) or peptides disrupting the DNMT1/PCNA, DNMT1/EZH2, DNMT1/HDAC1, DNMT1/DNMT3b and DNMT1/HP1 interactions promoted or enhanced in vivo tumorigenesis in a mouse glioma model." (PMID 23809695, 2013). "DNA methyltransferases DNMT3B, DNMT3A, and DNMT1 were comparatively overexpressed in the MS4A6A high expression subgroup, which might be the reason for MS4A6A hypomethylation in glioma tissues, leading to insight into upregulated mechanisms of MS4A6A in glioma." (PMID 36119086, 2022). "In glioma cells, DNA demethylation of promoters, following specific inhibition of DNMT1, DNMT3A, or DNMT3B, was not fully redundant suggesting the existence of different target patterns for these enzymes." (PMID 29449903, 2018). "Furthermore, transfection with miR-185 significantly reduced the levels of DNMT1 mRNA transcripts and protein expression in glioma cells, but did not affect the expression of DNMT3A and DNMT3B (data not shown)." (PMID 21962230, 2011).
Obesity (18 papers, 2015 to 2026). Accumulation of substantial excess body fat. "In this study, we demonstrated that female PD3bKO mice with Dnmt3b deficiency in adipocyte progenitor cells exhibit resistance to high-fat diet (HFD)-induced obesity and insulin resistance." (PMID 41596507, 2026). "Our data show that Dnmt3b deficiency in Myf5+-brown fat precursor cells inhibits thermogenic program in brown fat, decreases energy expenditure, and promotes diet-induced obesity and insulin resistance in female mice." (PMID 34439754, 2021). "To determine the molecular mechanism whereby Dnmt3b deficiency promotes diet-induced obesity, we performed a RNA-seq analysis using brown fat from HFD-fed female 3bKO mice and control fl/fl mice to unbiasedly examine the gene expression profiles." (PMID 34439754, 2021). "We found that the expression of DNA methyltransferases (DNMT3a and DNMT3b) in adipose tissue-derived macrophages was induced by HFD treatment or obesity-associated factors." (PMID 27530451, 2016). "In this context, our results would suggest an interesting link between obesity, altered DNMT3B expression and methylation defects that predispose to disease." (PMID 27169697, 2016). "In addition, Dnmt3b deficiency in brown fat also prevents diet-induced obesity and insulin resistance in female mice." (PMID 34947856, 2021). "In consistence with our prior findings on Dnmt1 or 3a, deletion of Dnmt3b at early stage of brown fat development using Myf5-Cre also promoted diet-induced obesity and insulin resistance, which was associated with the induction of myogenic program in brown fat." (PMID 34439754, 2021). "Here, we aimed to investigate the role of adipose progenitor cell Dnmt3b—an enzyme mediating de novo DNA methylation—in energy metabolism and obesity." (PMID 41596507, 2026). "In summary, we generated PD3bKO mice with Dnmt3b deficiency in adipocyte progenitor cells and demonstrated that these mice are resistant to HFD-induced obesity and insulin resistance." (PMID 41596507, 2026). "To investigate the role of Dnmt3b in diet-induced obesity, we fed PD3bKO mice with a high-fat diet (HFD) and characterized their metabolic phenotype." (PMID 41596507, 2026). "This is consistent with our recent report that deletion of Dnmt3b in mature brown adipocytes using Ucp-1 Cre driver ameliorates obesity in female mice." (PMID 41596507, 2026). "In contrast to these findings, the present study reveals that female PD3bKO mice with Dnmt3b deletion in adipocyte progenitor cells exhibit resistance to HFD-induced obesity." (PMID 41596507, 2026). "Further analysis revealed that the increased levels of adipose tissue-derived miR-548ag after the onset of obesity upregulated the expression of DPP4 by suppressing DNMT3B in the liver, leading to abnormal glucose tolerance and decreased insulin sensitivity." (PMID 36769291, 2023). "In obesity, DNMT3b regulates M2 macrophage polarization, and the deletion of DNMT3b induces M2 macrophage polarization." (PMID 37189665, 2023). "Here we aimed to study the role of Dnmt3b, a DNA methyltransferase involved in de novo DNA methylation, in the regulation of brown fat thermogenesis and obesity." (PMID 34947856, 2021). "Our data demonstrate that brown fat Dnmt3b is a key regulator of brown fat development, energy metabolism and obesity in female mice." (PMID 34439754, 2021). "Our data demonstrate that Dnmt3b plays an important role in the regulation of brown fat thermogenic function, energy metabolism and obesity in female mice." (PMID 34947856, 2021). "To determine the role of brown fat Dnmt3b in the regulation of diet-induced obesity, we generated a genetic model with deletion of Dnmt3b in brown fat-skeletal muscle lineage precursor cells (3bKO) by crossing Dnmt3b-floxed (fl/fl) mice with Myf5-cre mice." (PMID 34439754, 2021).
Obesity (continued). "To determine the role of brown fat Dnmt3b in the regulation of diet-induced obesity, we further conducted a metabolic characterization of body weight, energy metabolism and insulin sensitivity in female D3bKO mice fed HFD." (PMID 34947856, 2021). "Our data demonstrate that Dnmt3b plays an important role in the regulation of brown fat function, energy metabolism and obesity in female mice." (PMID 34439754, 2021). "Consistently, enhanced DNMT3B expression was proposed to contribute to deregulated adipose tissue macrophage polarization, inflammation and insulin resistance in obesity." (PMID 27169697, 2016). "Next, we verified which DNMTs among the three isoforms in mammals, DNMT1, DNMT3a and DNMT3b, were responsible for the obesity-induced R2 hypermethylation." (PMID 26139044, 2015). "Differential methylation is found within genes associated with obesity, epigenetic regulation and development, such as CETP, FOXP2, HDAC4, DNMT3B, KCNQ1 and HOX clusters." (PMID 25651499, 2015). "Moreover, we found that DNMT1, DNMT3A and DNMT3B in brown fat are critical for regulating thermogenesis and diet-induced obesity in mice." (PMID 41596507, 2026). "In addition, the expression of DNMTs (DNMT1, DNMT3a and DNMT3b) was quantified because they encoded the main enzymes involved in the methylation of DNA and previously we have detected a regulation of these genes after following a VLCKD in blood leukocytes of patients with obesity." (PMID 40140215, 2025). "The decreased trend in the expression levels of HDACs, DNMT1 and DNMT3b is consistent with lowering of the cytosine methylation status in both the promoter and CGI in the obesity group." (PMID 36045397, 2022). "Dnmt3b deletion in adipocyte progenitors enhanced thermogenic gene expression in brown adipose tissue, increased overall energy expenditure, and mitigated high-fat diet (HFD)-induced obesity in female mice." (PMID 41596507, 2026). "The DNMT3B gene (encoding DNA methyltransferase 3 beta, Q9UBC3) is not directly associated with obesity, but its involvement in DNA methylation can influence gene expression." (PMID 38666884, 2024). "Interestingly, DNA methyltransferase 3 beta (DNMT3B) showed the most significant difference in β-values between patients with and without obesity." (PMID 37512149, 2023). "It is not clear, however, whether Dnmt3b deletion in Myf5 lineage adipocytes would affect the formation of glycolytic beige adipocytes, contributing to the decreased energy expenditure and increased obesity observed in 3bKO mice." (PMID 34439754, 2021).
lymphoma (17 papers, 2012 to 2025). A malignant (clonal) proliferation of B- lymphocytes or T- lymphocytes which involves the lymph nodes, bone marrow and/or extranodal sites. "In terms of survival prediction using different DNMT expressions, previous studies showed that overexpression of DNMT1 or DNMT3b was associated with a poor prognosis in cancers of the lung, liver, and pancreas, lymphoma and other malignancies." (PMID 22768205, 2012). "DNMT1 and DNMT3B are the most frequently overexpressed and mutated DNMTs in lymphomas." (PMID 40299416, 2025). "The overexpression of DNMT3B is involved in the progression of lymphomas, particularly in Burkitt lymphoma (BL)." (PMID 40299416, 2025). "Although there were ample evidences for the cancer-promoting effects of DNMT3B, a study on its role in lymphoma suggested a different perspective." (PMID 36091786, 2022). "Overexpression of DNMT3B is related to drug resistance and the mTORC1 pathway is known to play an important role in the pathogenesis of lymphoma and various type of cancer, suggesting that these mechanisms may contribute to PDX resistance." (PMID 34332580, 2021). "Inactivation of the DNMT3B gene accelerated the development of lymphoma in DNMT3A-deficient mice, which indicates that the upregulation of DNMT3B inhibits disease progression in DNMT3A-deficient lymphoma." (PMID 32751889, 2020). "These promoters are demethylated in DNMT3B-deficient lymphoma, but not demethylated in DNMT3B-deficient precancerous thymocytes, which indicates that DNMT3B maintains cytosine methylation in cancer cells." (PMID 32751889, 2020). "Analysis of global genome methylation showed that in lymphomas of DNMT3B knockout mice hypomethylation and to a four-fold lesser extent also hypermethylation occurred suggesting that DNMT3B seems to play a role in hypomethylation and hypermethylation of intragenic regions and promoters." (PMID 22563479, 2012). "Moreover, it has been reported that DNMT3A may directly inhibit the upregulation of DNMT3B in lymphoma in animal models." (PMID 32751889, 2020). "Although DNMT3B has been reported to be regulated by c-Myc in mouse lymphoma, DNMT3B did not bind to c-Myc in HCT116 cells." (PMID 35327559, 2022). "Although a previous study reported that DNMT3B is regulated by c-Myc in mouse lymphoma, DNMT3B did not bind with c-Myc in HCT116 cells." (PMID 24822169, 2014).